MZF1 (myeloid zinc finger 1)
Diseases named in the same sentence as MZF1 in open-access papers (continued):
Sharing a sentence is not in itself a finding about the gene and the disease.
tumor (continued). "It has been previously shown that Ik-1 induces tumor suppressor effects primarily in hematopoietic cellular elements; nonetheless, the contribution of MZF1 to tumorigenesis is more diverse as it may induce oncogenic or tumor suppressor effects in hematopoietic and non-hematopoietic cells." (PMID 25884514, 2015). "Through an in-depth examination of experimental data related to immune cell infiltration, tumor microenvironment, TMB and MSI, a clearer understanding of MZF1’s involvement in cancer immunotherapy has been achieved." (PMID 40655141, 2025). "In the GSE120575 dataset, which includes tumor samples from 48 SKCM patients treated with checkpoint inhibitors, MZF1 expression was found predominantly in CD4 Tconv cells, Treg cells, CD8 T cells, and CD8 Tex cells within the SKCM microenvironment." (PMID 40655141, 2025). "In the present study, we highlight the pivotal role of MZF1 in regulating immune responses, particularly in immune cells such as CD4+ T cells and monocytes/macrophages, suggesting its involvement in the tumor immune microenvironment." (PMID 40655141, 2025). "By searching databases of patient-derived tumor samples, we found that MZF1 and SCAND2 RNA were more highly expressed in normal tissues than in tumor tissues in several cancer types." (PMID 36982267, 2023). "Moreover, MZF1 (Myeloid zinc finger 1), which is known as the oncogenic TF in various solid cancers, has a critical role in trans-differentiation of mesenchymal stem cells (MSC) into carcinoma-associated fibroblast (CAF)-like cells to promote tumor growth and metastases in BC." (PMID 35205770, 2022). "Furthermore, MZF1 is also vital in a protumorigenic microenvironment by activating the osteopontin (OPN) gene in mesenchymal stem cells (MSC), leading to transformation into cancer-associated fibroblasts (CAF) and the VEGF gene in tumor endothelial cells (TEC)." (PMID 36552758, 2022). "Forced expression of MZF1 induces malignant transformation of NIH3T3 cells, and initiates tumor formation in athymic mice." (PMID 32042322, 2020). "In vivo experiments using xenograft models revealed that stable over-expression of MZF1 promoted the tumorigenecity of SH-SY5Y cells, as displayed by increase in tumor growth, tumor weight, Ki-67 proliferative index, and elevated levels of HK2 and PGK1." (PMID 32042322, 2020). "Our findings provide insight into how MZF1-driven CDC37 expression promotes cancer progression and how SCAND1 functions as a potential tumor suppressor by repressing CDC37." (PMID 31181782, 2019). "Recent data has indicated that MZF1 is essential for the transcription of basal YAP1, and promotes tumor formation through stimulating the expression of YAP1." (PMID 30961610, 2019). "MZF1 was found crucial in osteopontin-driven MSC-to-CAF transformation, which promoted tumor growth in a microenvironment dependent manner." (PMID 28423538, 2017). "Stable transfection of MZF1 into SGC-7901 cells resulted in increased growth and tumor weight of subcutaneous xenograft tumors in athymic nude mice, when compared to those stably transfected with empty vector (mock)." (PMID 27259238, 2016). "Tumor-derived osteopontin (OPN) engenders MSC-to-CAF transformation in the microenvironment to promote tumor growth and metastasis via the OPN-myeloid zinc finger 1 (MZF1)-TGF-β1 pathway." (PMID 26690480, 2015). "Conversely, inhibition of myeloid zinc-finger 1 (MZF-1) expression, an oncogene or a tumor suppressor, can lead to decreased Fpn level, enhancing tumor cell growth." (PMID 25476483, 2015). "Furthermore, establishing tumor models that more closely mimic human physiological conditions, supported by advanced technologies, could pave the way for personalized treatment prediction systems based on MZF1 expression profiles, potentially incorporating artificial intelligence algorithms." (PMID 40655141, 2025).
tumor (continued). "The analysis revealed that MZF1 expression was significantly positively correlated with B cells, CAF cells, endothelial cells, eosinophils, CD4+ T cells, NKT cells, CD8+ T cells, mast cells, monocytes, and Tregs cells in most TCGA tumor types." (PMID 40655141, 2025). "Moreover, SCAND1 and MZF1 are mutually inducible and form oligomers that can reverse epithelial-to-mesenchymal transition (EMT), tumor growth, and migration by repressing EMT driver genes and mitogenic protein kinase (MAPK) genes." (PMID 36982267, 2023). "Furthermore, tumour-derived OPN also transforms MSCs into CAFs through the transcription factor, myeloid zinc finger 1 (MZF-1)-dependent TGF-β1 production, promoting tumour growth and metastasis." (PMID 36555218, 2022). "We believe that this study extends our knowledge about the regulation of aerobic glycolysis by transcription factor and its derived uPEP, and suggests that MZF1 and YY1 may be potential therapeutic targets for tumor progression." (PMID 32042322, 2020). "Furthermore, another study demonstrated that MZF1 is involved in the E6-mediated Foxhead box M1 (FOXM1)/NKX2-1 expression through the Wnt/β-catenin signalling pathway, resulting in tumour progression and poor outcomes in HPV-positive patients." (PMID 28720772, 2017). "We therefore propose the following model: more often than not, in tumor cells, the binding of MZF-1 and Elk-1 followed by clustering to the binding site of the PKCα promoter can stimulate PKCα expression." (PMID 26010542, 2015). "Moreover, MZF1 is also involved in activating or deactivating the PTEN gene, which is known as a tumor suppressor (module 2)." (PMID 25364730, 2014). "In addition, the T > C variation of rs10877887 may have strong affinity with Myeloid zinc finger 1 (MAF1), a transcription factor which can promote the activity of Axl promoter, resulting in tumor cell migration, invasion and metastasis." (PMID 30619739, 2018). "Besides, FPN could also be regulated by hypoxia inducible factor 2 (HIF2α), nuclear factor erythroid (Nrf2), metal regulatory transcriptioan factor 1 (MTF1), and myeloid zinc finger 1 (MZF1) at the transcriptional level in macrophages and tumor cells." (PMID 27768596, 2016). "Furthermore, SCAND1 and MZF1 expression was negatively correlated with TGFBR1, TGFBR2, and TGFBR3 gene expression, suggesting that SCAND1-MZF1 could reduce TGFβ receptors to narrow down TGFβ signals emanating from the microenvironment to tumor cells." (PMID 36552758, 2022).
cancer (50 papers, 2009 to 2025). A tumor composed of atypical neoplastic, often pleomorphic cells that invade other tissues. "It was observed that MZF1 exhibited a relatively weak prognostic association with a limited number of cancers." (PMID 40655141, 2025). "Studies show that MZF1 is associated with cancer immunotherapy markers, immune cell infiltration, and immune modulators." (PMID 40655141, 2025). "As research into MZF1 deepens, it has become clear that both its underexpression and overexpression are linked to cancer progression." (PMID 40655141, 2025). "AXL upregulation in cancer has been linked to transcription factors SP‐1 and MZF1, as well as STAT5 activation and hypoxia." (PMID 39395205, 2025). "The results indicated a strong association between MZF1 methylation and mRNA expression in most cancer types, with particularly pronounced correlations in BLCA, LGG, PRAD, ACC, and OV." (PMID 40655141, 2025). "Aberrant expression of MZF1 has been implicated in various cancer types, and can increase cancer cell proliferation, invasion and metastasis." (PMID 32899298, 2020). "During the last decade, MZF1 was shown to be implicated in the development of various types of solid cancers by enhancing cancer cell growth, migration and invasion." (PMID 31963147, 2020). "A recent computational study has tried to shed new light on MZF1 SCAN domain interactions by identification and analysis of cancer-specific mutations in the MZF1 SCAN domain." (PMID 31963147, 2020). "Amplifications in the MZF1 gene, as well as high MZF1 expression, are frequent in cancer, as shown by TCGA data, and MZF1 has been associated with cancer progression in a variety of solid tumors." (PMID 33333852, 2020). "Tian and co-workers have identified a mechanism by which MZF1 can affect gene expression via cancer-induced allelic mutations that result in a novel transcription factor co-operation at the promoter of the hepatocyte growth factor gene HGF." (PMID 31963147, 2020). "MZF-1 has also been implicated to regulate various factors in many cancers and cellular malignancies." (PMID 27542222, 2016). "Changes in MZF1 expression are linked to the prognosis of most cancer patients." (PMID 40655141, 2025). "Additionally, survival analysis indicated that MZF1 CNV is associated with lower OS in certain cancer types, including GBM, KIRC, LGG, UCEC, and KIRP." (PMID 40655141, 2025). "While its role in certain cancer types remains unclear, a deeper understanding of the underlying mechanisms of MZF1 may unveil additional biological features, thereby advancing its clinical application as a prognostic marker." (PMID 40655141, 2025). "The cBioPortal database helped explore potential MZF1 mutations across cancer types." (PMID 40655141, 2025). "It was consistently reported that the downregulation of MZF1 is associated with gastric tumourigenesis, suggesting that MZF1 could be an early predictive and prognostic biomarker of better prognosis in cancer patients." (PMID 36552758, 2022). "These mutations can alter the structure and functions of MZF1 in cancer." (PMID 36552758, 2022). "Moreover, MZF1 is involved in the transformation of mesenchymal stem cells into cancer-associated fibroblasts." (PMID 35350980, 2022). "In this study, 23 cancer-specific mutations were identified in the MZF1 SCAN domain, which could affect MZF1 function by changing its dimerization capacity directly or indirectly via gain or loss of possible post-translational modifications." (PMID 31963147, 2020). "MZF1 seems to be a central regulator of invasion-associated pericellular lysosome distribution and lysosome-mediated invasion of ErbB2 expressing highly invasive cancer cells." (PMID 31963147, 2020). "The alterations- and mutational landscape of MZF1 is strongly cancer-type dependent." (PMID 28018905, 2016). "Notably, high methylation of MZF1 could serve as a biomarker for reduced mortality risk, suggesting a potential protective role for MZF1 in early cancer prognosis." (PMID 40655141, 2025).
cancer (continued). "Moreover, simultaneous expression and appearance of other SCAN and SCAND domain-containing proteins and possible cancer-inducing mutations in them could also affect MZF1 function for example by directly or indirectly replacing the binding partners of MZF1." (PMID 31963147, 2020). "The results indicated that MZF1 expression was significantly negatively correlated with immune response genes in most cancer types." (PMID 40655141, 2025). "As the relationship between MZF1 and immunotherapy efficacy becomes increasingly evident, its potential as a cornerstone in future cancer immunotherapy research grows as well." (PMID 40655141, 2025). "In this study, the relationship between MZF1 expression levels and cancer cell proliferation was investigated by silencing MZF1 expression using siRNA." (PMID 40655141, 2025). "This study aimed to comprehensively analyze MZF1 expression and its mechanistic roles across various cancer types." (PMID 40655141, 2025). "RNA sequencing data were further analyzed via the TIMER database to explore the expression of MZF1 across various cancer types." (PMID 40655141, 2025). "Overall, MZF1 exhibits significant prognostic value in the majority of cancer patients, emerging as a promising prognostic biomarker, particularly in immune-related cancers." (PMID 40655141, 2025). "By analyzing the median expression levels of MZF1 across various cancers, the samples were classified into high-expression and low-expression groups, and GSEA and GSVA were performed to uncover the bioinformatics enrichment patterns associated with this gene." (PMID 40655141, 2025). "A spatial distribution map of MZF1 related to cancer tissue markers was created using the STOmics DB." (PMID 40655141, 2025). "The results showed that silencing MZF1 expression led to a significant decrease in the migration ability of cancer cells." (PMID 40655141, 2025). "MZF1 emerges as a promising prognostic biomarker and potential therapeutic target, offering novel avenues for cancer treatment strategies." (PMID 40655141, 2025). "MZF1 expression levels in various cancers were obtained from the Cancer Genome Atlas (TCGA) database." (PMID 40655141, 2025). "Spearman correlation analysis was conducted to examine the correlation between MZF1 gene expression and immune cell infiltration across various cancer types." (PMID 40655141, 2025). "Previous studies have revealed that the role of MZF1 in tumorigenesis is far from uniform across different cancer types." (PMID 40655141, 2025). "The interactions of ELK1 with MZF1, AR, and ER are some of the most reported in several cancer types, all credited with growth-related phenomena." (PMID 40862737, 2025). "In cervical cancer, MZF1 can be modulated via TGF-β1-ERK1/2 signaling to obtain the CK17-induced property of cancer stem cells." (PMID 37174714, 2023). "MZF1 has been shown to be essential for the regulation of proliferation, migration and invasion of malignant tumor cells 30-35." (PMID 36778111, 2023). "MZF1 is an oncogenic transcription factor that is activated by p95ErbB2 and is positively regulating lysosome-mediated invasion of cancer cells via cathepsin B expression." (PMID 37420029, 2023). "In conclusion, we have demonstrated that the cell stress-inducible SCAND and MZF1 repress the stress response in cancer." (PMID 36982267, 2023). "MZF1 has been indicated to regulate various factors in many cancers and induces migration, invasion, and in vivo metastatic potential in solid tumor cells." (PMID 35350980, 2022). "Collectively, our findings illustrated that MZF1-mediated miR-328-3p acted as a cancer suppressor in STAD progression via regulation of CD44, which suggested the possibility of the MZF1/miR-328-3p/CD44 axis as a novel promising therapeutic candidate for STAD." (PMID 35669102, 2022).
cancer (continued). "In our previous work in this model, we demonstrated cancer-secreted OPN acts through the transcription factor MZF1 to express the myCAF phenotype corresponding with increased α-SMA, VIM, and TEN-C." (PMID 36284815, 2022). "MZF1 expression is known to play a significant role in cancer progression; however, only little is known about how MZF1 can be inhibited." (PMID 36499054, 2022). "According to previous studies, MZF1 participates in the progression of diverse types of cancers via transcriptionally activating target genes." (PMID 35669102, 2022). "To date, a number of studies have presented a complicated interaction network for the regulated mechanism of MZF1 and its biofunctional role in multiple types of cancers." (PMID 35669102, 2022). "Through multiple signaling pathways, MZF1 can both promote cancer multiplication and inhibit cancer progression through apoptosis." (PMID 36358661, 2022). "Among the Krüppel family of proteins, MZF1 influences gene transcription and contributes to cancer progression." (PMID 36499054, 2022). "Our data also touch upon the prognostic importance of SCAND1 and MZF1 expression in evaluating several types of cancer." (PMID 36552758, 2022). "In this regard, MT2A protein exerts its anti-cancer effects through inactivation of NFKBIA (NFKB Inhibitor Alpha) subsequent binding to MZF1 (Myeloid Zinc Finger 1)." (PMID 36060520, 2022). "The majority of studies on MZF1 in cancer report that MZF1 functions as an oncogene in various solid cancers by regulating the expression of genes involved in cancer progression, EMT, extracellular matrix degradation, invasion, and angiogenesis." (PMID 31963147, 2020). "Many MZF1 target genes have a central role in cancer, and increased expression and/or activation of MZF1 induces cell growth, migration and invasion." (PMID 31963147, 2020). "The majority of the known MZF1 target genes are known cancer genes, whose activation is expected to promote cancer progression." (PMID 31963147, 2020). "The key to MZF1 function in cancer lies in its domain structure and in its post-translational modifications that are regulating its association with other factors, its activation status and its availability." (PMID 31963147, 2020). "Intriguingly, 17 of the 31 (55%) reported MZF1 target genes are somehow involved in EMT in other cancer studies." (PMID 31963147, 2020). "In this review, we summarize the research on MZF1 in cancer including its function and role in lysosome-mediated invasion and in the expression of genes involved in epithelial to mesenchymal transition." (PMID 31963147, 2020). "The mechanistical explanations of how MZF1 promotes cancer progression must rely on the activation of its specific target genes in cancer." (PMID 31963147, 2020). "We recently reported that the frequent amplification of MZF1 was observed in human cancers, further suggesting an oncogenic role for this factor." (PMID 31181782, 2019). "Since N-cadherin transcription was suppressed by MKD in TE2-CK2α cells, we concluded that MZF1 is a transcription factor responsible for CK2-mediated N-cadherin upregulation in cancer cells." (PMID 29540671, 2018). "MZF1 was expressed predominantly in the nucleus of both normal ductal epithelial cells and cancer cells." (PMID 29396433, 2018). "In summary, our results show that CK2 is able to phosphorylate and stabilize MZF1, thereby upregulating N-cadherin transcription during E-cadherin to N-cadherin switch in cancer cells." (PMID 29540671, 2018). "MZF1 knockdown (MKD) in N-cadherin-expressing cancer cells downregulates N-cadherin expression and reverts the morphology from spindle and fibroblast-like to a rounded, epithelial shape." (PMID 29540671, 2018). "The fact that these two processes can be regulated by different factors in cancer cells versus normal cells makes MZF1 and the lysosomal alterations it induces attractive targets for anti-cancer drug development." (PMID 29396433, 2018).